FGFR1 (fibroblast growth factor receptor 1)
Diseases named in the same sentence as FGFR1 in open-access papers (continued):
Sharing a sentence is not in itself a finding about the gene and the disease.
breast cancer (continued). "Another FGFR1–3 inhibitor, NVP-BGJ398, caused tumor regression in only one patient with FGFR1-amplified breast cancer in a phase I study." (PMID 30404198, 2018). "In fact, there are several studies showing different treatment outcomes of breast cancer women depending on the FGFR1 status." (PMID 29938003, 2018). "In breast cancer, FGFR1 amplification is the most frequent genomic aberration, whereas the FGFR2–4 gene amplifications and FGFR activating mutations are uncommon." (PMID 30011957, 2018). "In breast cancer patients with FGFR1 or FGF3 amplification, multikinase FGFR/VEGFR inhibitors have shown promising activity." (PMID 29743718, 2018). "N-cadherin promotes invasive ability through activating Fibroblast growth factor receptor 1 (FGFR1) signaling by inhibiting FGFR1 internalization in breast cancer cells." (PMID 29758011, 2018). "FGFR1 amplification and overexpression in certain breast cancer cells increases MAPK and PI3K-AKT activities." (PMID 30111373, 2018). "A cross-cancer effect is found between breast cancer and lung adenocarcinoma with HER2, HER2_pY1248, and EGFR_pY1068 levels decrease and 4E-BP1 levels increase associated with FGFR1 amplification for both histological tumor types." (PMID 30442178, 2018). "In vitro studies using breast cancer cell lines showed that FGF10 stimulation lead to the nuclear translocation of a 55 kDa C-terminal fragment of FGFR1, which in turn promoted the transcription of genes that stimulate cell migration and invasion." (PMID 30405704, 2018). "Published response rates were 33% in FGFR2 amplified gastroesophageal cancer and 12.5% in FGFR1 amplified breast cancer." (PMID 30181810, 2018). "Gene amplification and protein overexpression of FGFR1 was detected in squamous cell lung carcinoma (~20%), small-cell lung carcinoma (6%) and breast cancers (10–13%), including hormone receptor-positive or triple-negative breast cancers." (PMID 30404198, 2018). "The FGFRs harbour genetic aberrations such as amplifications of FGFR1, FGFR2 and FGFR4 and mutations in FGFR2 and FGFR4 genes in breast cancer." (PMID 29455658, 2018). "A recent study applied a pre-clinical mammary tumor model to show that FGFR1 inhibitor treatment leads to initial rapid regression which is, nevertheless, finally followed by tumor recurrence." (PMID 28775339, 2017). "AZD4547 is also undergoing a Phase I/II clinical trial in combination with fulvestrant versus fulvestrant alone in ER+ breast cancer patients with FGFR1 amplification (NTC01202591)." (PMID 28030802, 2017). "Of the 94 enrolled patients initially, partial responses were seen in 4 FGFR3 mutated bladder cancers, 2 FGFR1 amplified SqCLC, and a reduction in tumor burden was seen in FGFR2 fusion cholangiocarcinoma as well as in FGFR1 amplified breast cancer." (PMID 28030802, 2017). "FGFR1 TKI induces protective autophagy through suppressing AKT/mTOR signaling pathway in FGFR1-amplified breast cancer cell lines." (PMID 28558758, 2017). "The next highest amplifications were reported in FGFR1 gene and found predominantly in breast cancer cases." (PMID 28371134, 2017). "The promising anti-cancer effects of PD173074 have also been translated into a xenograft tumor model of breast cancer in BALB/c mice where 4T1 xenograft tumor growth was remarkably suppressed by this FGFR1/FGFR3 dual inhibitor." (PMID 28900173, 2017). "For example, resistance to tamoxifen has been associated with constitutive activation of MAPK and the subsequent expression of cyclin D1 in FGFR1-amplified breast cancer cell lines." (PMID 28183331, 2017). "AZD4547-induced regulation of Wnt/β-catenin signaling is particularly important since breast cancers that overexpress both FGFR1 and Wnt are correlated with high patient mortality." (PMID 28900173, 2017). "FGFR1 gene amplification has been reported in numerous malignancies including breast cancer and squamous cell carcinoma of lung cancer, head and neck cancer, and esophageal cancer." (PMID 28915719, 2017).
breast cancer (continued). "We also observed consistent results between MIP microarray and NGS in detecting HER2 and FGFR1 amplification in breast cancer, which supports findings from a previous study." (PMID 28125801, 2017). "Functional studies showed that overexpression of miR-361-5p suppressed the glycolysis and proliferation of breast cancer cells by targeting FGFR1, the invasion and metastasis by targeting MMP-1." (PMID 29132384, 2017). "Using both non-transformed and transformed cell lines, we demonstrate that breast cancer cells express a number of FGF ligands that are known to activate FGFR1." (PMID 28968431, 2017). "In the FGFR1-amplified breast cancer group, a 20.2% reduction in tumor size was found after dovitinib but no reduction in tumors with less than six copies of FGFR1." (PMID 28980224, 2017). "This implies that similar to breast cancer, the 8p11-12 amplicon in sqNSCLC extends beyond the FGFR1 gene resulting in elevated expression of several genes, potentially contributing to oncogenesis and/or modulating the cellular response to FGFR1." (PMID 26905262, 2016). "The overall FGFR1 expression rate in breast cancer was 14.3%, occurring predominantly in Lum B cancers (24.9%)." (PMID 26673008, 2016). "Fibroblast growth factor receptor 1 (FGFR1) has been suggested to be the candidate gene for 8p11–12 amplification in breast cancer and its therapeutic/prognostic value is explored." (PMID 26673008, 2016). "Recent investigations have highlighted the potential clinical values of FGFR1 as a therapeutic target and prognostic biomarker in breast cancers." (PMID 26673008, 2016). "We evaluated FGFR1 expression in a large cohort of breast cancer by immunohistochemistry, correlated with the tumor clinic-pathologic features, biomarkers expression, and patient's survival." (PMID 26673008, 2016). "Here, we observed a positive association of FGFR1 with the transcriptional factor SOX2 with neural stem cell renewal, and particularly with neuroendocrine differentiation in breast cancer." (PMID 26673008, 2016). "While most previous studies focused on the FGFR1 amplification in clinical breast cancers as a group, FGFR1 protein expression in different molecular breast cancer subtypes and its association with other important biomarkers and prognosis are far from clear." (PMID 26673008, 2016). "In this study, the expression of FGFR1 in a large cohort of breast cancer was evaluated and correlated with various clinic-pathological features, biomarker expression and outcome, as well as with different breast cancer molecular groupings." (PMID 26673008, 2016). "Tumor reductions were also observed in cholangiocarcinoma with an FGFR2 gene fusion, and FGFR1-amplified breast cancer." (PMID 27409839, 2016). "We further used pooled samples to carry out DNA FISH for six genes previously reported to contribute to driver mutations in breast cancer: MYC, FGFR1, CCND1, HER2, TOP2A, and ZNF217." (PMID 26008969, 2015). "The Small cell fraction also showed copy number increases in six target genes (FGFR1, Myc, CCND1, HER2, TOP2A and ZNF217) associated with breast cancer." (PMID 26008969, 2015). "All breast cancer cells secrete high mount of FGF2 as well as express higher FGFR2 protein than FGFR1, and the level is much higher than in Hs 578Bst cells." (PMID 26575424, 2015). "Analysis of copy number abnormalities has shown a consistently high level of amplification of chromosomal region 8p11 containing the FGFR1 coding region in early-stage breast cancers, resulting in overexpression of FGFR1." (PMID 26581390, 2015). "For example, FGFR1 amplification was found in in-situ carcinomas and low-grade ER positive breast cancers and in early stage lung cancers." (PMID 26555375, 2015). "Six genes have been reported to contribute to about 44% of driver mutations in breast cancer (copy number increase or amplicons): MYC, FGFR1 (Chromosome 8); CCND1 (Chromosome 11); HER2, TOP2A (Chromosome 17); and ZNF217 (Chromosome 20)." (PMID 26008969, 2015).
breast cancer (continued). "The mRNA and protein expression level of FGFR1 and other FGFRs were examined in several lines of breast cancer and osteosarcoma cells and corresponding normal cells using Taqman real-time quantitative PCR and Western blot analysis." (PMID 26201468, 2015). "A number of early phase clinical trials have selected breast cancers with FGFR1 amplification, providing preliminary evidence of activity for small molecule FGFR inhibitors in FGFR1 amplified breast cancer." (PMID 25932042, 2015). "The importance of cooperative effects between Wnt and FGFR1 signaling observed in mouse mammary tumor models is supported by our recent analysis of patient outcomes in human breast cancer." (PMID 26581390, 2015). "While either active WNT signaling or FGFR1 amplification/overexpression is associated with poor disease-specific survival, tumors with both pathways activated exhibited the worst prognosis, supporting that the two pathways may cooperate to drive tumor progression in human breast cancer." (PMID 26581390, 2015). "Using flanking primer sets, we were able to identify human mammary tumor samples that not only upregulated FGFR1 expression but also aberrantly excluded the α exon as compared to their matched normal samples (patient 1 and patient 7)." (PMID 24618085, 2014). "In breast cancer, ER-regulated genes including FGFR1 and IRS1, and ERK1-regulating genes including IRF6 and TOM1L1, were aberrantly methylated." (PMID 24842468, 2014). "In human, gene amplification of FGFR1 in 22% of squamous cell lung cancer, and 10% of ER-positive breast cancer." (PMID 25594045, 2014). "FGFR1 gene amplification was reported firstly as a potential therapeutic target in breast cancer 16–18." (PMID 24861215, 2014). "For FGFR1 amplification, 9 of 17 studies were in lung cancer, 4 studies were in breast cancer, and the other 4 studies were about oral and tongue squamous cell carcinoma, and oral squamous cell carcinoma." (PMID 25171497, 2014). "Cancer associated fibroblasts are involved in tumor formation and progression where miR-15 and miR-16 regulate FGF2 and FGFR1 in prostate cancer and miR-18 in breast cancer." (PMID 24597607, 2014). "Recently, we demonstrated that FGFR1 cleavage and nuclear translocation results in upregulation of an invasive gene signature in breast cancer." (PMID 24503018, 2014). "In this article, we showed that FGFR1 is amplified in lung cancer, breast cancer and, rarely, in pancreatic cancer and squamous cell cancer, whereas FGFR2 amplification mainly occurs in gastric cancer and breast cancer." (PMID 25171497, 2014). "FGFR1 amplification contributes to high metastatic potential and resistance to endocrine therapy of human breast carcinomas and is thought to be a major contributor to the poor prognosis of the luminal B subtype." (PMID 24098698, 2013). "In line with this, the chromosomal regions 8p11-12 and 10q26 are consistently amplified in human breast cancers, and some of the genes within this region that are amplified are FGFR1 and FGFR2." (PMID 23900974, 2013). "They suggested a role for FGFR1 amplification in the progression of breast cancer including in situ-to-invasive transition." (PMID 23270564, 2012). "It is important to note that FGFR1 amplification enhances tamoxifen resistance, which is particularly clinically relevant in male breast cancer, as endocrine therapy is often indicated in these patients." (PMID 22527098, 2012). "In conclusion, our data show that the growth-promoting effects of FGFR1 are prominent in S115 breast cancer cells and tumors." (PMID 23185502, 2012). "Our results therefore suggest that FGFR1 amplification play an important role in the progression of breast cancer, including the in situ to invasive transition, as well as initiation." (PMID 22863309, 2012). "FGFR1 amplification, and hence increased FGFR1 signaling, therefore seems to contribute to early breast cancer invasion; that is, the in situ to invasive transition." (PMID 22863309, 2012).
breast cancer (continued). "Approximately 10% of all and 16–23% of luminal type B breast carcinomas show FGFR1 gene amplification; one of the most common focal amplifications observed in breast cancer." (PMID 23056402, 2012). "Expression of FGFR1 itself was maintained by FGFR-mediated signaling and exposure of S115 and MCF-7 breast cancer cells to FGF-8b increased FGFR1 level." (PMID 23185502, 2012). "In conclusion, our results demonstrate that FGFR1 is crucial for S115 breast cancer cell proliferation and tumor growth and angiogenesis, whereas FGFR2 and FGFR3 are less critical for the growth of these cells." (PMID 23185502, 2012). "Since FGFR1 expression has been shown to play pivotal roles in primary breast cancer tumorigenesis, we sought to analyze the status of FGFR1 gene in a metastatic setting of lobular breast carcinoma, since promising FGFR1 inhibitors has been recently developed." (PMID 23270564, 2012). "Pools of S115 mouse breast cancer cells expressing shRNA against FGFR1, 2 and 3 were created by lentiviral gene transfer, resulting in cells with downregulated expression of FGFR1, FGFR2 or FGFR3 (shR1, shR2 and shR3 cells, respectively) and shLacZ controls." (PMID 23185502, 2012). "Although amplification of HER2, C-MYC, CCND1 and FGFR1 has been reported in breast cancers, their role in the progression of in situ to invasive breast carcinoma is unclear." (PMID 22863309, 2012). "The FGFR1 gene is amplified in approximately 10% of breast cancers, and a correlation between amplification and FGFR1 expression levels has been examined in several studies." (PMID 23185502, 2012). "In order to study the role of different FGFRs in breast cancer cell proliferation and tumor growth, we individually silenced each of the endogenous FGFRs (FGFR1, 2 and 3) in S115 breast cancer cells." (PMID 23185502, 2012). "The three cases with FGFR-1 amplification matched with those primary breast carcinomas showing FGFR-1 amplification." (PMID 23270564, 2012). "In mouse models of prostate and breast carcinoma, FGFR1 activation via an inducible regulation system accelerated progression to malignancy." (PMID 22899908, 2012). "Meaburn and Misteli analyzed the radial distribution of four genes related to cell survival, mobility and migration, namely AKT1, VEGF, ERBB2, and FGFR1 in a cell-model of breast cancer." (PMID 20958983, 2010). "The 7 angiogenesis genes present in the list were also predominantly down-regulated (e.g. NRP1, JMJD6, CYR61, FGFR1) and again the impact of these genes on the carcinogenesis of breast cancer cells has been described." (PMID 21062462, 2010). "We demonstrate in the present study that FGFR1 amplification is found in 8.7% of breast cancers, which is in agreement with previous studies." (PMID 17397528, 2007). "Given that up to 8.7% of all breast cancers harbour FGFR1 amplification and that this amplification is an independent predictor of overall survival, further studies analysing the FGFR1 as a potential therapeutic target for breast cancer patients are warranted." (PMID 17397528, 2007). "Recent studies have demonstrated that specific FGFR1 amplification correlates with gene expression and that FGFR1 activity is required for the survival of a FGFR1 amplified breast cancer cell line." (PMID 17397528, 2007). "Targeting FGFR1 signalling with RNA interference or with the SU5402 FGFR1 tyrosine kinase inhibitor has been shown to decrease cell survival in a breast cancer cell line with FGFR1 amplification." (PMID 17397528, 2007). "Taken together, our results demonstrate that FGFR1 amplification is found in 8.7% of breast cancers and is an independent predictor of outcome." (PMID 17397528, 2007). "FGFR1 expression has been shown to play pivotal roles in mammary development and breast cancer tumourigenesis." (PMID 17397528, 2007).
breast cancer (continued). "Previous analysis of 8p12 subregional amplifications in breast cancer pointed to the amplified FGFR1 subregion as the best prognostic marker of bad disease evolution among other 8p amplifications." (PMID 17040570, 2006). "Furthermore, tasurgratinib, an FGFR1–3 selective inhibitor, and fulvestrant, an ET, showed antitumor activity in preclinical models of ET-resistant ER+ breast cancer." (PMID 40227585, 2025). "Likewise, although arising from distinct cellular contexts, aberrant FGFR1/STAT3 activation has been shown to trigger cell death in breast cancer cells." (PMID 41304754, 2025). "Given that the alpelisib-fulvestrant combination is a clinical standard for ER+/HER2- breast cancer, our results suggest that patients with high FGFR1 expression might benefit from this modified regimen, thereby enhancing clinical outcomes in resistant cases." (PMID 40510030, 2025). "Therefore, the associations we report with ER-negative breast cancer genes and African ancestry should be taken with caution, but the associations we reported with ER-positive related breast cancer genes (e.g., GATA3, FGFR1) are likely correct." (PMID 41162424, 2025). "Among such alterations, FGFR1 amplification is most prominent in breast cancer." (PMID 41514604, 2025). "This suggests that FGFR1-induced alpelisib resistance is mediated by signaling that not only compensates for PI3K inhibition but also drives key cellular processes essential for breast cancer progression." (PMID 40510030, 2025). "Given the potential interplay between FGFR1 and alpelisib’s target, it is crucial to investigate whether and how FGFR1 overexpression may induce alpelisib resistance in breast cancer." (PMID 40510030, 2025). "Pazopanib has also shown efficacy in FGFR1-amplified breast cancer and uterine carcinosarcoma." (PMID 39590377, 2024). "In summary, our study has demonstrated that FGFR1 amplification in ER + breast cancer cells activate a collateral JAK-STAT pathway and leads to p21 upregulation, which inhibits the proliferation of cancer cells and enhances their stemness properties with FGF2 simulation." (PMID 38553760, 2024). "Moreover, the divergent effects of FGF2 on cell cycle and stemness state in breast cancer cells harboring FGFR1 amplification are still unclear." (PMID 38553760, 2024). "Additionally, the protease granzymeB (GrB) is responsible for the cleavage of FGFR1, leading to the nuclear localization of FGFR1 cleavage and the invasion of breast cancer cells into the stroma." (PMID 38820302, 2024). "The paradoxical growth effects may help explain the failure of clinical trials with FGFR inhibitor as monotherapy in breast cancer patients with FGFR1 amplification." (PMID 38553760, 2024). "This unexpected outcome, particularly in microenvironments with elevated FGF ligand levels, could have detrimental clinical effect in patients, such as ER + breast cancer patients with high FGFR1 and FGF2 expression." (PMID 38553760, 2024). "Identifying FGFR1 levels in breast cancer samples could assist in predicting cell progression and choosing anti-FGFR inhibitors for future cancer treatment." (PMID 38553760, 2024). "For breast cancer, our focus turned to the drug Brivanib and the gene FGFR1." (PMID 38754409, 2024). "FGFR1 is activated and transferred into the nucleus to promote metastasis of breast cancer." (PMID 37490511, 2023). "Importantly, the inhibition of SOX4 and FGFR1 translation by zotatifin was observed in both mouse tumors and human breast cancer cell lines, indicating the conserved regulation of these genes by eIF4A." (PMID 37874652, 2023). "Upregulation of FGFR1 contributes to the progression and resistance in lung and breast cancer." (PMID 37715207, 2023). "Notably, 1 (12.5%) of 8 breast cancer patients with FGFR1 amplification and 3 (33.3%) of 9 gastroesophageal cancer patients with FGFR2 amplification had confirmed responses with AZD4547." (PMID 37980453, 2023).